NCAPG (non-SMC condensin I complex subunit G)
Diseases named in the same sentence as NCAPG in open-access papers (continued):
Sharing a sentence is not in itself a finding about the gene and the disease.
renal clear cell carcinoma (continued). "To further consolidate the hypothesis that NCAPG promoted the progression of renal clear cell carcinoma, we explored the effects of NCAPG on the proliferation of renal clear cell carcinoma." (PMID 35601741, 2022). "We further found that the expression of CDK1 was upregulated in renal clear cell carcinoma compared with normal tissue, and the expression of NCAPG was associated tightly with overall survival and disease-free survival in renal clear cell carcinoma, which was consistent with the results of NCAPG." (PMID 35601741, 2022). "NCAPG might provide a new diagnosis and prognosis-related biomarker for lots of patients with renal clear cell carcinoma." (PMID 35601741, 2022). "The results consolidated the hypothesis that NCAPG promotes the proliferation and progression of renal clear cell carcinoma via mediating CDK1." (PMID 35601741, 2022). "NCAPG might provide a new diagnosis-related biomarker and therapeutic target for lots of patients with renal clear cell carcinoma." (PMID 35601741, 2022). "NCAPG/CDK1 complex might provide a new treatment strategy for lots of patients with renal clear cell carcinoma." (PMID 35601741, 2022). "NCAPG might promote the proliferation of renal clear cell carcinoma via mediating CDK1." (PMID 35601741, 2022). "Knockdown NCAPG could restrain the proliferation of renal clear cell carcinoma." (PMID 35601741, 2022). "Finally, we have reasons to believe that NCAPG promoted the proliferation and progression of renal clear cell carcinoma via mediating CDK1, and NCAPG/CDK1 complex might provide a new strategy for the treatment of renal clear cell carcinoma." (PMID 35601741, 2022). "To further explore the correlation between CDK1 and NCAPG in renal clear cell carcinoma, we extracted the correlation between NCAPG and CDK1 from online database, and the results showed that CDK1 was positively related with NCAPG (R = 0.73; P < 0.01)." (PMID 35601741, 2022). "GraphPad was used for data analysis, and t-test and χ2 analysis were used to analyze the correlation between NCAPG/CDK1 and renal clear cell carcinoma." (PMID 35601741, 2022). "The next aim of our study is to explore the specific relationship between NCAPG and CDK1; the effects of NCAPG/CDK1 complex on the invasion and progression of renal clear cell carcinoma will be the next direction." (PMID 35601741, 2022). "As a result, the role of CDK1 in renal clear cell carcinoma still remained unclear, and the relationship between NCAPG and CDK1 in renal clear cell carcinoma needs further exploration." (PMID 35601741, 2022). "To further explore the relationship between NCAPG and CDK1, we explored the effects of CDK1 on the proliferation of renal clear cell carcinoma." (PMID 35601741, 2022). "And knockdown NCAPG could significantly restrain the proliferation and progression, NCAPG was tightly related with CDK1, and NCAPG/CDK1 complex might be the internal mechanism of NCAPG promoting the proliferation of renal clear cell carcinoma." (PMID 35601741, 2022).
acute myeloid leukemia (3 papers, 2016 to 2021). Acute myeloid leukemia (AML) is a group of neoplasms arising from precursor cells committed to the myeloid cell-line differentiation. "Besides, we showed that the expression of NCAPG was decreased in acute myeloid leukemia (LAML)." (PMID 35211508, 2021).
psoriasis (3 papers, 2023 to 2025). An autoimmune condition characterized by red, well-delineated plaques with silvery scales that are usually on the extensor surfaces and scalp. "Moreover, NCAPG has been identified as a susceptibility gene for psoriasis, underscoring its role in both diseases and justifying its investigation as a key gene in cell cycle regulation." (PMID 40406126, 2025). "In psoriasis, the five diagnostic hub genes (KIF4A, DLGAP5, NCAPG, CCNB1, and CEP55) were predominantly expressed in keratinocytes, with significantly higher expression levels in patient samples compared to controls." (PMID 40406126, 2025). "It is considered possible that NCAPG may function as a low-frequency frameshift gene and participate in the development of psoriasis." (PMID 40560938, 2025). "This integrative approach highlighted KIF4A, DLGAP5, NCAPG, CCNB1, and CEP55 as key shared biomarkers for both psoriasis and CD." (PMID 40406126, 2025). "In the psoriasis validation cohort (GSE14905), the AUC values for KIF4A, DLGAP5, NCAPG, CCNB1, and CEP55 were 0.96, 0.97, 0.96, 0.98, and 0.93, respectively." (PMID 40406126, 2025). "In the psoriasis dataset (GSE13355), the AUC values for KIF4A (AUC = 0.99), DLGAP5 (AUC = 1), NCAPG (AUC = 0.99), CCNB1 (AUC = 0.99), and CEP55 (AUC = 0.99) exhibited exceptional diagnostic performance, with all values exceeding 0.7." (PMID 40406126, 2025).
gastric adenocarcinoma (2 papers, 2022 to 2025). "NCAPG Targeting: NCAPG knockdown reverses Wnt/β-catenin activation, reduces EMT markers (e.g., Snail suppression with E-cadherin upregulation), and induces apoptosis in gastric adenocarcinoma." (PMID 40951343, 2025). "Additionally, studies on stomach adenocarcinoma (STAD) suggest that through the Wnt/β-catenin signaling pathway by promoting epithelial-mesenchymal transition, NCAPG overexpression inhibits apoptosis in cardia adenocarcinoma." (PMID 36238529, 2022).
pancreatic adenocarcinoma (2 papers, 2021 to 2023). "Zhang et al22 manifested that NCAPG overexpression leads to aberrant activation of the PI3K/AKT signaling pathway, fostering pancreatic adenocarcinoma cell proliferation." (PMID 37553792, 2023).
sarcoma (2 papers, 2021 to 2023). A usually aggressive malignant neoplasm of the soft tissue or bone. "By evaluating NCAPs in normal and sarcoma tissues using the GEPIA database, we noticed significantly higher expression patterns of NCAPD2, NCAPG, NCAPH, NCAPG2, and in sarcoma samples compared to normal tissues." (PMID 37192046, 2023). "Six members of the NCAPs family, including NCAPD2, NCAPG, NCAPH, NCAPD3, NCAPG2, and NCAPH2, have been found in different types of sarcomas." (PMID 37192046, 2023). "The high expression of NCAPD2, NCAPG, NCAPH, NCAPD3, and NCAPH2 were all correlated with the relapse-free survival of sarcoma patients, HR = 2.76 (p = 3.3e-05), 2.72 (p = 0.0012), 2.71 (p = 0.0026), 1.87 (p = 0.01) and 2.08 (p = 0.029) respectively." (PMID 37192046, 2023). "GEPIA database showed that high expression of NCAPD2, NCAPH, NCAPG and NCAPG2 had a significant correlation with poor overall survival of sarcoma patients (P < 0.05)." (PMID 37192046, 2023). "In this study, ONCOMINE, GEPIA, Kaplan-Meier plotter, DAVID (KEGG and GO analysis), and TIMER datasets were utilized to study the high expression, prognosis analysis, signal pathway and immune correlation of NCAPD2, NCAPG, NCAPH, NCAPD3, NCAPG2, and NCAPH2 in sarcoma for the first time." (PMID 37192046, 2023). "However, our research proved that the high expression of NCAPG in sarcoma is relevant to the lower OS and DFS of sarcoma patients." (PMID 37192046, 2023). "Up to now, NCAPD2, NCAPG, NCAPH, NCAPD3, NCAPG2, and NCAPH2 have not been mentioned in sarcoma, except NCAPG mentioned in Ewing sarcoma." (PMID 37192046, 2023). "In the Kaplan-Meier Plotter database, high expression of NCAPD2, NCAPG, NCAPH, and NCAPD3 was correlated with poor overall survival in sarcoma patients (p < 0.05), HR = 2.23 (p = 0.00016), 1.63 (p = 0.015), 1.83 (p = 0.0025), and 1.63 (p = 0.024), respectively." (PMID 37192046, 2023).
Cirrhosis (1 paper, 2020). A chronic disorder of the liver in which liver tissue becomes scarred and is partially replaced by regenerative nodules and fibrotic tissue resulting in loss of liver function. "The expression of NCAPG seemed to differ substantially between some indicated features, including cirrhosis, TNM staging, AFP level." (PMID 32300299, 2020).
colitis (1 paper, 2024). Inflammation of the colon. "A PPI network based on DEGs was constructed using STRING, and a highly interconnected cluster was identified as a potential functional molecular complex of colitis, including 8 hub genes, that is, NDC80, PBK, CEP55, RRM2, ASPM, NCAPG, TOP2A, and CDKN." (PMID 38661103, 2024).
colon cancer (1 paper, 2021). "However, CD44, NCAM1,SYP, and NCAPG showed higher expression levels than NCM-460 in the majority of colon cancer cell lines." (PMID 35155186, 2021).
diabetes (1 paper, 2022). "Nonetheless, none of the expression of ASPM, CDC20, DLGAP5, BUB1B, CDCA8, and NCAPG was related to BMI and diabetes." (PMID 36186000, 2022).
endometriosis (1 paper, 2025). The growth of functional endometrial tissue in anatomic sites outside the uterine body. "Our study has identified eight potential mitosis hub genes (KIF4A, BUB1B, NEK2, FBXO5, KIF11, CENPE, CCNA2, and NCAPG) that exhibit excellent diagnostic properties for endometriosis." (PMID 40772274, 2025). "Then, we identified 11 potential mitosis-related downregulated hub genes, among which eight genes (KIF4A, BUB1B, NEK2, FBXO5, KIF11, CENPE, CCNA2, and NCAPG) showed good diagnostic properties of endometriosis and two genes (CCNA2, CENPE) were closely related to infertile endometriosis." (PMID 40772274, 2025). "We used the GSE25628 dataset to detect the expression of selected target genes, and the results showed that the differential expression of eight MRHGs (KIF4A, BUB1B, NEK2, FBXO5, KIF11, CENPE, CCNA2, and NCAPG) between control and endometriosis patients was consistent with predictions." (PMID 40772274, 2025).
fibrosis (1 paper, 2024). the formation of excess fibrous connective tissue in an organ or tissue in a reparative or reactive process. "To date, there have been limited reports on the relationships between CCNB2, NCAPG, KIF20A, KIF11, and BUB1B with SSc or fibrosis." (PMID 38343538, 2024).
high-grade gliomas (1 paper, 2023). "A previous study has shown that NCAPG expression level was much higher in pediatric high-grade gliomas (pHGG) than in pediatric LGG (pLGG), and the knockdown of NCAPG slowed cell proliferation, which has indicated that NCAPG play an important role in gliomagenesis." (PMID 36703644, 2023).
leiomyosarcoma (1 paper, 2023). An uncommon, aggressive malignant smooth muscle neoplasm, usually occurring in post-menopausal women. "NCAPG was upregulated in Myxofibrosarcoma, Pleomorphic Liposarcoma, and Leiomyosarcoma with 3.118 (p = 4.55E-14), 3.051 (p = 7.64E-10) and 2.633 (P = 6.60E-8) fold changes." (PMID 37192046, 2023).
liver cirrhosis (1 paper, 2019). "Furthermore, high NCAPG and positive liver cirrhosis improved the AUC to 0.81 (P = 0.000)." (PMID 31022357, 2019). "Similarly, NCAPG expression alone and when in combination with the presence of liver cirrhosis could discriminate early HCC recurrent disease with an AUC of 0.76 (P = 0.028) and 0.82 (P = 0.008), respectively, in this validation patient cohort." (PMID 31022357, 2019). "Here we demonstrated that NCAPG transcript level in combination with liver cirrhosis could discriminate early recurrent tumors from nonrecurrent tumors with an AUC of >0.80 in 2 independent datasets, whereas NCAPG protein level can correctly identify 7 out of the 8 early recurrent tumors." (PMID 31022357, 2019).
liver fibrosis (1 paper, 2024). "Among these 47 SDE-identified genes, NCAPG and NHLRC1 were those that best at discriminating patients who achieved regression of liver fibrosis (LSMred>50%)." (PMID 39911830, 2024).
metastatic tumors (1 paper, 2024). "Firstly, we performed the TF enrichment analysis between primary tumors and metastatic tumors, and finally, seven TFs were identified as differentially expressed TFs, including CBX2, CDX2, FOXA2, KLF4, NANOG, NCAPG, and TFAP2A, which was demonstrated in a heatmap and a volcano plot." (PMID 38702698, 2024).
neuroblastoma (1 paper, 2023). Neuroblastoma (NB) is the most common solid, extracranial childhood tumor. "The findings of the study indicated a significant association between the expression of NCAPG and the outcomes of patients with neuroblastoma." (PMID 37834394, 2023). "Moreover, it was observed that NCAPG exhibited significant upregulation in individuals with neuroblastoma who had MYCN amplification, high-risk, high-stage disease, and tumor advancement." (PMID 37834394, 2023). "NCAPG protein expression was assessed using immunohistochemistry on tumor specimens obtained from neuroblastoma patients for the present study." (PMID 37834394, 2023). "Based on the DepMap database analysis, we identified NCAPG as a possible treatment target for neuroblastoma." (PMID 37834394, 2023). "The Kaplan–Meier curves showed that neuroblastoma patients who had highly expressed NCAPG had poorer EFS and OS (p = 0.0138 and 0.0213, respectively)." (PMID 37834394, 2023). "The findings of these investigations provided evidence in favor of the conjecture that NCAPG functions as an oncogenic factor in human neuroblastoma cell lines, as its suppression impeded the cells’ ability to proliferate, migrate, and invade." (PMID 37834394, 2023). "Our study investigated the function of NCAPG in neuroblastoma by knocking down NCAPG expression in SH-SY5Y and SK-N-BE cells with shRNA plasmid vectors." (PMID 37834394, 2023). "The NCAPG gene plays an oncogenic role in neuroblastoma cells and comprises cell cycle and apoptosis." (PMID 37834394, 2023). "Immunohistochemistry was used to measure NCAPG protein expression levels in 40 neuroblastoma tissue samples." (PMID 37834394, 2023). "The analysis of the GSE49710 dataset revealed a significant correlation between elevated levels of NCAPG expression and an unfavorable prognosis among individuals diagnosed with neuroblastoma." (PMID 37834394, 2023). "NCAPG downregulation inhibited the colony formation abilities of neuroblastoma cells in colony formation assays." (PMID 37834394, 2023). "The study conducted a correlation analysis between NCAPG expression and various clinical characteristics of neuroblastoma patients." (PMID 37834394, 2023). "The results of the univariate analysis demonstrated a statistically significant correlation between the increased expression of NCAPG and unfavorable overall survival in patients diagnosed with neuroblastoma (p = 0.033)." (PMID 37834394, 2023). "Our subsequent work would continue to concentrate on the possibility of NCAPG in neuroblastoma clinical management and further mechanistic investigations to explore potential therapeutic targets." (PMID 37834394, 2023). "The correlation between NCAPG protein high expression and OS time in neuroblastoma patients was analyzed using univariate and multivariate methods to establish its independent prognostic significance." (PMID 37834394, 2023). "But, further research is needed to understand how NCAPG is expressed in neuroblastoma and its role in biology." (PMID 37834394, 2023). "The signature gene, NCAPG, was downregulated in neuroblastoma cells to explore its impact on various cellular processes." (PMID 37834394, 2023). "The function of NCAPG in neuroblastoma cell apoptosis was examined using flow cytometry." (PMID 37834394, 2023). "As a next step, we looked at NCAPG’s biological role in neuroblastoma cells." (PMID 37834394, 2023).
neuroblastoma (continued). "Furthermore, we confirmed the mRNA and protein expression of NCAPG in four distinct cell lines of neuroblastoma." (PMID 37834394, 2023). "Neuroblastoma progression patients expressed significantly higher levels of NCAPG." (PMID 37834394, 2023). "GSEA was conducted to explore the cellular roles of NCAPG in neuroblastoma." (PMID 37834394, 2023). "In conclusion, it appeared that NCAPG functions as an oncogene during neuroblastoma development." (PMID 37834394, 2023). "Neuroblastoma proliferation, invasion, and migration were decreased by inhibiting NCAPG expression." (PMID 37834394, 2023). "NCAPG protein was highly expressed in 47.5% (19/40) of neuroblastoma tissues." (PMID 37834394, 2023). "The suppression of NCAPG prevented neuroblastoma cells from proliferating, migrating, and invading." (PMID 37834394, 2023). "The present work showed that NCAPG knockdown reduced neuroblastoma cell progression and may serve as a basis for further investigation into diagnostic indicators and therapy targets for neuroblastoma." (PMID 37834394, 2023). "Therefore, NCAPG protein overexpression could be considered a prognostic biomarker for neuroblastoma." (PMID 37834394, 2023). "Silencing the NCAPG gene in SH-SY5Y and SK-N-BE confirmed its significance in neuroblastoma." (PMID 37834394, 2023). "Neuroblastoma with amplified MYCN expressed higher NCAPG than neuroblastoma without amplified MYCN." (PMID 37834394, 2023).
osteosarcoma (1 paper, 2021). A usually aggressive malignant bone-forming mesenchymal neoplasm, predominantly affecting adolescents and young adults. "RFC4, CDK3, CDC45 and NCAPG were found to be associated with osteosarcoma for the first time in our analysis, and thus could be novel diagnostic/prognostic biomarkers or treatment targets." (PMID 34156352, 2021).
serous ovarian cancer (1 paper, 2021). "This showed that higher expressions of CDCA3, CENPF, NCAPG, RRM2, UBE2C, and NBEA were associated with worse OS regardless of serous ovarian cancer stages." (PMID 34577856, 2021).
squamous cell carcinoma (1 paper, 2022). A carcinoma arising from squamous epithelial cells. "Kaplan-Meier survival analysis showed that NCAPG expression was negatively correlated with survival in NSCLC patients (n = 156, p = 0.003), particularly in elderly patients (≥ 60 years old) (n = 84, p = 0.0022), adenocarcinoma (n = 92, p = 0.0239), and squamous cell carcinoma (n = 43, p = 0.0296)." (PMID 35180865, 2022).
Stillbirth (1 paper, 2015). Death of the fetus in utero after at least 22 weeks of gestation. "We then identified two well-known genes, NCAPG and its near neighbor LCORL within 37.2–37.5Mb on OAR6, which are reported to be involved in fetal growth, stillbirth, and carcass size in sheep and other livestock." (PMID 26083354, 2015).